IL17F (interleukin 17F)
Diseases named in the same sentence as IL17F in open-access papers (continued):
Sharing a sentence is not in itself a finding about the gene and the disease.
Cirrhosis (2 papers, 2017 to 2025). A chronic disorder of the liver in which liver tissue becomes scarred and is partially replaced by regenerative nodules and fibrotic tissue resulting in loss of liver function. "Post-hoc testing indicated that IL-17F levels were significantly higher in patients with compensated cirrhosis compared to those with acute decompensation (p = 0.022) and ACLF (p = 0.036)." (PMID 41200179, 2025). "These interpretations, however, are speculative and warrant future experimental validation in studies directly investigating IL-17F-mediated NF-κB signaling in cirrhosis." (PMID 41200179, 2025). "Our study demonstrated that concentrations of IL-17F, IL-23 and IL-1b were significantly lower in patients with acute decompensation and ACLF compared to those with compensated cirrhosis, indicating a progressive decline with increasing disease severity." (PMID 41200179, 2025). "Levels of IL-17F, IL-23, and IL-1β levels were significantly lower in patients with AD and ACLF compared to those with compensated cirrhosis." (PMID 41200179, 2025). "In this prospective observational study, we analyzed circulating levels of IL-23, IL-17A, IL-17E, IL-17F, IL-1β, and IL-1RA in 127 patients with compensated cirrhosis, acute decompensation (AD), or ACLF in the absence of active infection." (PMID 41200179, 2025).
co-infection (2 papers, 2014 to 2022). "We showed that if IL-1β, TNFα and OSM were present in uninfected excisional skin lesions, IL-17A, IL-17F and IL-22 were specifically produced after S. aureus and P. aeruginosa co-infection of the lesions." (PMID 36275755, 2022). "In addition, the diminished systemic production of IL-2, IL-17A and IL-17F also indicate a more extensive impairment in Th1 and Th17 responses in co-infection settings." (PMID 25211342, 2014).
cystic fibrosis (2 papers, 2017 to 2022). Autosomal recessive disorder caused by pathogenic variants in the CFTR gene (cystic fibrosis transmembrane conductance regulator), which encodes a chloride and bicarbonate channel expressed in epithelial cells, and follow the diagnosis criteria. "Higher levels of IL17F have been found in the sputum of patients with cystic fibrosis undergoing pulmonary exacerbation, in saliva of patients with periodontitis, in psoriatic skin lesions or in sera of patients with atopic asthma or systemic sclerosis." (PMID 36292624, 2022).
dilated cardiomyopathy (2 papers, 2015 to 2017). Cardiomyopathy which is characterized by dilation and contractile dysfunction of the left and right ventricles. "However, after stratification by gender, the IL17F was associated with dilated cardiomyopathy in male patients that present the T/C-C/C genotypes, suggesting that the presence of the rare allele (C) might be associated with the disease in these patients." (PMID 28470012, 2017).
fatty liver (2 papers, 2016 to 2021). "In an analysis using mice, IL-17A-, IL-17F-, and IL-17RA-deficient mice showed liver steatosis in a fatty liver model due to a methionine choline-deficient diet, but the degree of liver dysfunction was significantly lower than that of wild-type mice." (PMID 33918456, 2021). "However, despite these similarities, MCDD-fed IL-17RA-/-, IL-17A-/- and IL-17F-/- mice exhibited increased levels of hepatic steatosis compared to WT mice, as determined by hepatic triglyceride deposition." (PMID 26895034, 2016).
gastritis (2 papers, 2020 to 2024). Inflammation of the stomach. "Among the inflammatory cytokines evaluated in this study, IL-17A, IL-17F, and IL-22 can play a crucial role in developing gastritis, especially moderate gastritis, in infected patients with H. pylori." (PMID 39807418, 2024). "Th17 cell-related pro-inflammatory cytokines (IL-17a and IL-17f) also contribute to gastritis, while Th1-independent gastritis could be ascribed to the hyper-activation of the Th17 cell subset." (PMID 32974219, 2020). "The levels of IL-2, IL-17A, IL-17F, IL-22, TNF-α, and IFN-γ were significantly higher in patients with mild and moderate gastritis than Hp- group (P≤0.05)." (PMID 39807418, 2024). "The amounts of IL-2, IL-4, IL-17A, IL-17F, IL-22, TNF-α, and TFN-γ were significantly different in patients with gastritis compared with Hp- subjects." (PMID 39807418, 2024).
gestational hypertension (2 papers, 2024 to 2025). "Therefore, the aim of our study was to assess the population of Treg (CD4+CD25+FoxP3+) and Th17 lymphocytes, as well as the intracellular expression of IL-17A, IL-17F, IL-21, and IL-22 in women with PIH (including preeclampsia)." (PMID 41156157, 2025).
Graves disease (2 papers, 2017 to 2025). Graves' disease is an autoimmune disorder that leads to overactivity of the thyroid gland (hyperthyroidism).It is caused by an abnormal immune system response that causes the thyroid gland to produce too much thyroid hormones. "Serum cytokine levels (including IL-6, IL-9, IL-17A, IL-17F, and IL-22) exhibited significant differences between healthy subjects and patients with newly diagnosed hyperthyroid Graves’ disease (GD) under varying serum iodine concentration (SIC)." (PMID 40895623, 2025).
hepatic (2 papers, 2016 to 2017). "In contrast, IL-17RA-/-, IL-17A-/- and IL-17F-/- mice fed MCDD primarily displayed centrilobular, macrovesicular hepatic lipidosis with mild to moderate levels of hepatic inflammation based on H&E staining." (PMID 26895034, 2016).
Hypertension (2 papers, 2021 to 2025). The presence of chronic increased pressure in the systemic arterial system. "These cells also express high levels of RORγt transcription factor-dependent proinflammatory prohypertensive cytokines IL-17A and IL-17F that contribute to hypertension." (PMID 34777016, 2021). "Although Th17 cells with intracellular IL-17F/IL-22 co-expression constituted <3% of the CD4+ population overall, the more than threefold increase compared to controls suggests their involvement in hypertension in pregnancy." (PMID 41156157, 2025).
knee osteoarthritis (2 papers, 2019). "The most important finding was that polymorphisms of IL-17A(rs2275913) and IL-17F(rs763780) gene associate with the risk of knee osteoarthritis in different ethnics." (PMID 31842922, 2019). "Our research suggests that IL-17A(rs2275913) and IL-17F(rs763780) gene polymorphisms are a risk factor for knee osteoarthritis (p < 0.05)." (PMID 31842922, 2019). "By a pilot study with small population, IL-17 polymorphisms (IL-17A rs2275913 and IL-17F rs763780) showed a more potential risk factor in knee osteoarthritis (OA) in our recruited subjects." (PMID 30658595, 2019). "The aim of this study was to determine whether IL-17A(rs2275913) and IL-17F(rs763780) polymorphisms confer susceptibility to knee osteoarthritis." (PMID 31842922, 2019). "Bafrani found that IL-17A(rs2275913) gene may be a protective factor against knee osteoarthritis while the IL-17F(rs763780) gene may be a risk factor for knee osteoarthritis." (PMID 31842922, 2019).
lung disease (2 papers, 2019 to 2023). "For example, the IL-17 family of mediators (including IL-17 A, IL-17F and to a lesser extent IL-17 B, C D, and E) is a highly relevant target for CF lung disease given its role in combating bacterial and fungal pathogens, and its association with airway inflammation and PEs in CF." (PMID 37809107, 2023).
lymphedema (2 papers, 2009 to 2024). Excess fluid collection in tissues, causing swelling. "In our study, we found augmented induction of IL-17A, IL-17F, IL-21, and IL-23 in patients with filaria-induced lymphedema." (PMID 19381284, 2009). "To address the role of Th17 cells in filarial lymphedema, we examined the expression of IL-17A, IL-17F, IL-21 and IL-22 as well as the upstream inducing cytokines IL-23, IL-6 and IL-1β in PBMCs of lymphedema patients following BmA or PPD stimulation." (PMID 19381284, 2009). "Babu and collaborators demonstrated that the expression of the Th17 cytokines IL-17A, IL-17F, IL-21, and IL-23 was significantly upregulated in filaria-infected patients with lymphedema, suggesting a role for Th17 cells in the pathogenesis of filaria-induced pathology." (PMID 38587077, 2024). "Notably, expression of the Th17 family of cytokines—IL-17A, IL-17F, IL-21, and IL-23—was also significantly upregulated by BmA stimulation in lymphedema patients." (PMID 19381284, 2009). "Most effector cytokines known to be produced by Th17 cells—IL-17A, IL-17F, and IL-21 (with the exception of IL-22)—are induced at significantly higher levels in patients with lymphedema, suggesting an important role for these cytokines in development of this disease process." (PMID 19381284, 2009).
Miscarriage (2 papers, 2021 to 2024). A pregnancy that ends at a stage in which the fetus is incapable of surviving on its own, defined as the spontaneous loss of a fetus before the 22th week of pregnancy. "The serum of miscarriage patients has been shown to contain significantly higher levels of specific inflammatory cytokines (IL-2, IL-17A, IL-17F, TNF-α, and IFN-γ)." (PMID 39203483, 2024). "Here we report that IL-2, IL-17A, IL-17F, TNF-α, and IFN-γ are significantly increased in serum of miscarriage patients." (PMID 33731680, 2021). "Multiplex analysis revealed markedly increased serum levels of IL-2, IL-17A, IL-17F, tumor necrosis factor-α (TNF-α), and IFN-γ in miscarriage patients than those in the controls." (PMID 33731680, 2021). "The current study also found that serum levels of IL-2, IL-17A, IL-17F, TNF-α, and IFN-γ were markedly increased in miscarriage patients compared to the controls." (PMID 33731680, 2021).
myocarditis (2 papers, 2020 to 2024). Myocarditis is a condition that is characterized by inflammation of the heart muscle (myocardium). "Several cytokines such as IFN-γ, IL-17A, IL-17F promote early tissue damage and progression of DCM of myocarditis." (PMID 38741130, 2024). "Th17 cells and related cytokines like IL-17A, IL-17F, IL-22, TNF-α are the major regulators of the late or chronic phase of myocarditis, and IL-17A and IL-17F are signature cytokines." (PMID 32269577, 2020).
nasal polyps (2 papers, 2009 to 2017). "Our results suggest that IL-17A and IL-17F, but not IL-17E, contribute to infiltration of Th17 cells and DCs into upper airway inflammatory sites such as nasal polyps through the production of MIP-3α/CCL20 by fibroblasts." (PMID 23283206, 2009). "Here we sought to quantify IL-17A, IL-17F, IL-21, and IL-22 cytokines produced by Th17 cells in mucosal tissue and peripheral blood of CRSwNP, CRS without nasal polyps (CRSsNP) and control patients." (PMID 29311948, 2017). "Combined stimulation with TNF-α plus IL-17A or IL-17F, but not IL-17E, synergistically induced release of MIP-3α/CCL20 by the nasal polyp fibroblasts." (PMID 23283206, 2009).
oral squamous cell carcinoma (2 papers, 2020 to 2022). "We found that increased salivary concentration of IL-17A, IL-17F, and TNF-α is associated with advanced oral squamous cell carcinoma." (PMID 32855976, 2020).
parasitemia (2 papers, 2019 to 2023). "IFN-γ and monocyte chemoattractant protein-1 (MCP-1) production induced in T. cruzi-infected infants correlated with parasitemia, whereas the plasma levels of IL-17A, IL-17F, and IL-6 were less parasite load-dependent." (PMID 38133693, 2023). "We also determined a correlation between plasma cytokine concentrations and parasitemia before treatment, finding only IL-17A and IL-17F have significant positive correlations (r = 0.38; P = 0.001 and r = 0.44; P = 0.003, respectively)." (PMID 31553732, 2019).
pemphigus (2 papers, 2019 to 2024). Pemphigus is a group of rare autoimmune diseases that cause blistering of the skin and mucous membranes (mouth, nose, throat, eyes, and genitals).This conditioncan occur at any age, but often strikes people in middle or older age. "In line with previous human pemphigus studies, the data presented here confirm the overexpression of IL-17A, IL-17F, IL-17RA, IL-23A, and IL-23R in canine PF skin." (PMID 38393106, 2024). "Further studies will be needed to evaluate whether inhibitors of the IL-17 pathway (e.g., IL-17A, IL-17A/IL-17F, and IL-23A) could be used to treat the pemphigus group of blistering diseases in humans and dogs." (PMID 38393106, 2024).
periodontal disease (2 papers, 2015 to 2022). "IL-17A and IL-17F have a very similar amino acid sequence and both play similar functions and have the ability to induce chemokines which is crucial to the neutrophil recruitment and activation, the first wall in the periodontal diseases." (PMID 26339129, 2015).
Psoriasiform dermatitis (2 papers, 2020 to 2025). A skin abnormality characterized by redness and irritation, with thick, red skin that displays flaky, silver-white patches (scales). "Other members of the IL-17 family, such as IL-17C and IL-17F, are expressed prominently in psoriasiform dermatitis, and they enhance innate defenses in epithelial cells." (PMID 40920623, 2025). "Resolvin D1 alleviated the IMQ-induced psoriasiform dermatitis and reduced the expression of IL-23, IL-17A, IL-17F, IL-22, and TNF-α in the lesions." (PMID 32751360, 2020).
schizophrenia (2 papers, 2013 to 2020). A major psychotic disorder characterized by abnormalities in the perception or expression of reality. "Ratios of cytokine concentrations within the same axis may also be a marker of immune pathway activation, as has been reported for IL-17/TGF-β ratio in schizophrenia or IL-17F/IL-22 ratio in chronic hepatitis C virus infection." (PMID 23968496, 2013). "Similar to our results, reduced levels of IL-17F were measured in drug-naїve schizophrenia patients, while others have published negative results." (PMID 33182582, 2020).
skin infection (2 papers, 2018 to 2020). An inflammatory process affecting the skin, caused by bacteria, viruses, parasites, or fungi. "Mice deficient in IL-17A or IL-17F have proved prone to skin infections caused by gram-positive bacteria such as S. aureus." (PMID 29590259, 2018). "Mice that produce neither IL-17A nor IL-17F are susceptible to skin infection by S. aureus, since TH17-type cytokines IL-17A and IL-17F critically recruit neutrophils to clear S. aureus." (PMID 33271763, 2020).
steatosis (2 papers, 2016 to 2017). Increased lipid within the cytoplasm of cells. "Further, we show that deficiency of IL-17A, IL-17F or IL-17RA results in increased steatosis, but reduced steatohepatitis when fed MCDD." (PMID 26895034, 2016). "In contrast, IL-17RA-/-, IL-17A-/-, and IL-17F-/- mice, despite increased steatosis, exhibited significant protection from hepatocellular damage compared to WT controls." (PMID 26895034, 2016).
abortion (1 paper, 2016). the ending of pregnancy by removing a fetus or embryo before it can survive outside the uterus. "However, the percentages of Th2 (p = 0.00001) and Th17/Th2 (producing IL-4 plus IL-17A, IL-17F and IL-22) (p = 0.001) T cell clones were significantly higher in the decidua of normal pregnancy compared to decidua of women suffering from unexplained recurrent abortion." (PMID 26798325, 2016).
Acanthamoeba infection (1 paper, 2025). "Several cytokines, such as interferon-gamma (IFN-γ), interleukin (IL)-4, IL-10, IL-17A, IL-17F, and IL-22, are rapidly produced and secreted in response to Acanthamoeba infection." (PMID 40109888, 2025). "Several cytokines, for example, IFN-γ, IL-4, IL-10, IL-17A, IL-17F, and IL-22, were reported to rapidly produce and secrete in response to the Acanthamoeba infection but not IL-1β cytokine." (PMID 40109888, 2025).
acute GVHD (1 paper, 2020). "In this study, we dissect the role of donor-derived IL-17A and IL-17F for endothelial and epithelial permeability in an experimental acute GVHD model using single- (Il17a-/-, Il17f-/-) and double-deficient (Il17af-/-) donor T cells." (PMID 32251446, 2020). "Therefore, our data points to potential redundancy of IL-17A and IL-17F in the pathology of acute GVHD." (PMID 32251446, 2020).
acute pancreatitis (1 paper, 2022). An acute inflammatory process that leads to necrosis of the pancreatic parenchyma. "RNA‐seq data discovered that compared to untreated mice, IL‐23a, IL‐17a, and IL‐17f were remarkably increased while cell cycle‐related molecules, including ATM, Cdk2, and Chk2, were decreased in the mice with acute pancreatitis." (PMID 35634959, 2022). "qPCR data also confirmed the upregulated levels of IL‐23a, IL‐17a, and IL‐17f and the downregulated levels of ATM, Cdk2, and Chk2 in the pancreatic tissues of mice with acute pancreatitis." (PMID 35634959, 2022).
adenovirus infection (1 paper, 2019). "ILC3 production of IL-17F during adenovirus infection was shown to lead to optimal effector CD8+ T cell responses in the liver, which further exacerbates viral-induced liver hepatitis in mice." (PMID 30893756, 2019).
allergic conjunctivitis (1 paper, 2024). "In a recent mouse model of allergic conjunctivitis, stimulation and activation of the Th17 cytokines IL-17A and IL-17F, as well as the specific transcription factor RORγt, suggest that developmental enhancement can exacerbate Th2 dominant allergic inflammation in conjunctivitis." (PMID 39295864, 2024).
amyloidosis (1 paper, 2024). A disorder characterized by the localized or diffuse accumulation of amyloid protein in various anatomic sites. "Amyloidosis in the liver was recovered in IL-17A-/KCASP1Tg mice and IL-17AF-/KCASP1Tg mice but not in IL-17F-/KCASP1Tg mice." (PMID 39519167, 2024).
ankylosis (1 paper, 2021). Fixation and immobility of a joint. "Moreover, a bispecific antibody neutralizing both cytokines, bimekizumab, was more effective than antibodies targeting either IL-17A or IL-17F implying that such dual inhibition might prevent the ankylosis observed in patients with axSpA." (PMID 34539646, 2021).
atopic asthma (1 paper, 2017). An asthma that is characterized by symptoms that are triggered by an allergic reaction caused by inhaled allergens such as dust mite allergen, pet dander, pollen and mold. "Scatter plot correlation between serum IL-17F with expression of mRNA IL-17F levels in atopic asthma F and patient is shown here." (PMID 28606156, 2017). "According these data suggest that levels of mRNA IL-17F and IL17F might be useful parameters for the diagnosis of atopic asthma patient." (PMID 28606156, 2017).
B-cell neoplasm (1 paper, 2020). A group of heterogeneous lymphoid tumors generally expressing one or more B-cell antigens or representing malignant transformations of B-lymphocytes. "A previous report associated IL-17F expression with a bad clinical outcome of T-cell lymphomas, whereas for B-cell neoplasms, the scenario was unclear." (PMID 32913559, 2020).
brucellosis (1 paper, 2019). Brucellosis is a bacterial infection that spreads from animals to people via unpasteurized dairy products or by exposure to contaminated animal products or infected animals. "Although both IL-17A and IL-17F are cytokines mainly secreted by Th17 cells, the expression of IL-17A and IL-17F in patients at different stages is not consistent, suggesting that they may play different roles in regulating the immune mechanism of brucellosis." (PMID 31467933, 2019).
Candidemia (1 paper, 2025). A form of invasive candidiasis where species of CANDIDA are present in the blood. "The IL-17 family consists of IL-17A to IL-17F; the roles of IL-17A and IL-17C cytokines have been of great interest in the context of candidemia." (PMID 41229429, 2025).
cardiac hypertrophy (1 paper, 2021). "IL-17F/A signaling was found in the top canonical pathways of HT modified genes under resting unstimulated conditions, whereas cardiac hypertrophy signaling was identified among the pathways affected by HT-IL-1β." (PMID 34836245, 2021).
cardiomyopathy (1 paper, 2017). A disease of the heart muscle or myocardium proper. "The results suggest the possible involvement of the polymorphisms of IL17A and IL17F in the susceptibility to chronic Chagas disease and in development and progression of cardiomyopathy." (PMID 28470012, 2017).